EGFR (epidermal growth factor receptor)
Diseases named in the same sentence as EGFR in open-access papers (continued):
Sharing a sentence is not in itself a finding about the gene and the disease.
tumor (continued). "In addition, Ki67 staining was performed to investigate the proliferation activity of tumor tissue with RPN2 or EGFR silencing, and our results revealed that the expression level of Ki67 was higher in control mice than in mice inoculated with HCT116-shRPN2 and HCT116-shEGFR." (PMID 29069815, 2017). "No sequencing mutations were observed for EGFR exons 18 to 22 in tumor tissue or cells in culture." (PMID 29285236, 2017). "However, the effect of EGFR/HER2 signal blockade on the tumor immune microenvironment is unclear." (PMID 28969039, 2017). "Moreover, the prognosis was strongly associated with tumor grade but not EGFR mutation status for both DFS and OS." (PMID 29065153, 2017). "For example, EGFR amplification and mutation can result in the overexpression of various downstream effector molecules such as VEGF, interleukin-18, and angiopoietin-like 4 to make synergic effect on tumor neovascularization, consequently altering the vascular structure and function." (PMID 29097933, 2017). "We conducted this retrospective study to investigate whether microwave ablation (MWA) of primary tumor sites plus epidermal growth factor receptor-tyrosine kinase inhibitors (EGFR-TKIs) could improve survival in advanced non small cell lung cancer (NSCLC) with EGFR mutations." (PMID 28915624, 2017). "When intravenously injected in tumor bearing nude mice, the tumors could be detected as early as one hour after injection, and images of dissected tissue sections confirmed high uptake in the tumor, and liver, both displaying high EGFR-expressing levels, and kidney, the main excreting organ." (PMID 28336959, 2017). "Notably, variant VκF94A + VHP97A, which had the lowest intrinsic EGFR affinity of ~150 nM (~250-fold less than parental DuetMab), induced the most significant tumor selectivity, while no substantial reduction in potency against the “target tumor” was observed." (PMID 28067257, 2017). "To determine whether targeted therapies affected PD-L1 expression and infiltration of CD8+ lymphocytes, we analyzed the TPS for PD-L1 expression and CD8+ TILs in paired tumor biopsies obtained from patients before starting EGFR-TKIs and after developing resistance to EGFR-TKIs (n = 47, cohort B)." (PMID 29296194, 2017). "The median plasma cfDNA concentration of tumor-tissue EGFR M+ patients was lower than that of EGFR M- patients (9.61 ng/mL vs. 12.82 ng/mL, P = 0.049), possibly indicating that less cfDNA is released from the tumors of the EGFR M+ patients than from those of the EGFR M- patients." (PMID 28052016, 2017). "Therefore, EGFR expression may serve as a valuable biomarker for predicting tumor prognosis in GC patients." (PMID 28199988, 2017). "The combination approach including JNJ- 61186372 could prevent or delay resistance to EGFR TKI, by acting on multiple clonal populations with varying EGFR mutations within the same tumor, more complete suppression of the EGFR pathway, and by parallel inhibition of c-Met." (PMID 27786612, 2017). "However, whether tumours with these different factors benefit from anti-EGFR therapy is still confusing and uncertain." (PMID 28513565, 2017). "In addition, after systemic intravenous delivery of cRGD-siEGFR, we showed that down-regulation of EGFR in mouse tumors could substantially slow tumor growth, and low toxicity or innate immune response was induced in vivo." (PMID 28181832, 2017). "EGF-induced tumor cell proliferation and migration is suppressed when Cav-1 binds to the EGFR, suggesting that Cav-1 may play a role in maintaining the EGFR in an inactive state, with dissociation from Cav-1 promoting EGFR activation." (PMID 29141593, 2017). "Therefore, we proposed that the stemness property could be regulated by EGFR-mediated epigenetic modifications for maintaining the undifferentiating tumor status." (PMID 28787001, 2017).
tumor (continued). "However, the increased expressed level of these genes may not always be translated into the corresponding proteins, which are directly competing with antibodies to bind on the EGFR on tumour cells." (PMID 28032593, 2017). "Additionally, this could also be due to the amplification of EGFR and subsequent in vivo gain of EGFR-dependence of tumor cells in mouse tumor models." (PMID 28572590, 2017). "Interestingly, emerging data are demonstrating the feasibility of detecting EGFR mutations in ctDNA from urine samples, potentially providing a completely non-invasive alternative sample type in the absence of the preferred tumor tissue." (PMID 27980215, 2017). "Indeed, EGFR amplification and mutation are invariably expressed in a heterogeneous manner, and the presence of EGFRvIII in a minor population of GBM cells has been shown to confer a more aggressive tumor phenotype through paracrine mechanisms." (PMID 28797294, 2017). "Moreover, 7A7, an anti-murine EGFR mAb, could elicit strong tumor-specific CTL responses in hosts by inducing ICD of tumor cells in an Fc-independent manner." (PMID 28855903, 2017). "Thus, by blocking EGFR function in tumor residential macrophages during EGFR antagonist treatment this supply of cytokines may be interrupted, leading to diminished tumor growth and tumor-intrinsic instability." (PMID 28970798, 2017). "Furthermore, we investigated whether RPN2 could regulate EGFR glycosylation in xenograft tumor tissues, and immunofluorescence staining showed that EGFR localization was altered and protein expression decreased by RPN2 silencing." (PMID 29069815, 2017). "Therefore c-Met gene amplification could bypass the inhibited EGFR phosphorylation kinase pathway and activate downstream signal transduction, thus facilitating the tumor cells proliferation and developing resistance to EGFR-TKI." (PMID 29050366, 2017). "Thus, variations in EGFR have the potential to promote tumor growth and survival." (PMID 28427242, 2017). "Therefore although rarely detected, de novo T790M could have existed in a very minor part of tumor cells and amplified during EGFR-TKIs treatment." (PMID 29245913, 2017). "In addition, the selective tumour eliminationsuggested that anti-EGFR-functionalized LM nanocapsules were efficientlyinteracted with HT29 cells and could destroy cancer by powerful photothermal andROS generation properties of LM nanocapsules." (PMID 28561016, 2017). "To better understand the efficacy of the combination therapy over time, we sought to classify which initial tumor cell subpopulations could eventually lead to therapeutic failure when treated with different concentrations of EGFR TKIs in combination with crizotinib, trametinib or vemurafenib." (PMID 28287179, 2017). "Therefore, finding EGFR T790M in tumor specimens after initial therapy with first- and second-generation EGFR TKIs is important to identify patients who may respond favorably to third-generation EGFR TKIs." (PMID 26862733, 2016). "Therefore, we speculate that the simultaneous inhibition of IL10 and EGFR may achieve greater anti-tumor effects compared with the individual inhibition of IL10 or EGFR." (PMID 26956044, 2016). "However, due to the invasive procedures required to obtain tumor tissues, not all patients can provide enough high-quality tissues for EGFR mutation analysis." (PMID 27619632, 2016). "We sought to find out i) if tumor subclones expressing a mutated EGFR ectodomain or activating RAS mutations exist in HNSCC tumors before cetuximab-based treatment and ii) if such subclones emerge or expand under the selective pressure of EGFR-directed antibody treatment in this disease." (PMID 27119512, 2016). "In conclusion, we established a dual target, light-controlled delivery strategy for monoclonal antibodies with EGFR-targeting immune liposomes, light-controlled release from endosomes and light-mediated inactivation of Ki-67 as molecular switch to provoke efficient tumor cell elimination." (PMID 27246531, 2016).
tumor (continued). "From pharmacodynamic perspective, the advantages of the combined therapy of brivanib and cetuximab may occur because it not only inhibits VEGF-induced angiogenesis of tumor cells, but also inhibits EGFR signaling pathways in parallel to further inhibit the proliferation of tumor cells." (PMID 27806321, 2016). "Interestingly, it also has been shown that tumor resistant to EGFR inhibitors may switch to the survivin network for survival and recurrence." (PMID 27456457, 2016). "The tumor did not harbor either EGFR or, KRAS mutations or ALK rearrangement." (PMID 27150058, 2016). "Generally, in primary tumours acquired resistance to anti-EGFR antibodies could result from compensatory mechanisms for reduced EGFR signaling as well as genetic alterations in the EGFR-RAS-RAF-MEK signaling pathway or other receptor tyrosine kinases." (PMID 27643613, 2016). "A very serious issue that has not been answered is whether all tumor sites have epidermal growth factor receptor (EGFR) mutations." (PMID 28293661, 2016). "Thus, development of new methods is needed for the detection of EGFR mutations in patients with little or no available tumor sample." (PMID 27081078, 2016). "Several adjunctive variables, not investigated in the present study, such as the level of stromal Lymphocyte Tumor Infiltration (sTIL) and PIK3CA mutations, EGFR or PTEN expression, along with distinct intrinsic molecularly-defined subtypes, may have influenced outcomes." (PMID 26910921, 2016). "Moreover, they indicated rare coexistence of the KRAS gene mutations with deletion in EGFR gene that was observed only in primary tumor but not in corresponding metastatic sample." (PMID 25902737, 2016). "We screened 3543 NSCLC patients treated with EGFR TKI at our hospital (Sun Yat-Sen University Cancer Center) during January 2008 to March 2014 for negativity of EGFR mutation, record of detailed medical history and availability of enough tumor tissue samples for IHC analysis." (PMID 26646697, 2016). "In addition, recent studies suggest the potential roles of EGFR-mediated signaling in regulation of expression of the checkpoint molecule, PD-L1, in tumor cells, although the correlation between mutant EGFR status and PD-L1 expression in tumor tissues has been inconclusive." (PMID 27833557, 2016). "Thus, it appears that EGFR may be a potential tumor antigen for CAR NK cells to target for the treatment of BCBMs." (PMID 27050072, 2016). "Thus, oHSV-1, EGFR-CAR NK cells, and their combination are capable of selectively targeting and destroying tumor cells of BCBMs and all of them, especially the combination, may have an optimal efficacy in patients with tumor cells expressing EGFR." (PMID 27050072, 2016). "Given that heterodimers of EphA2 and EGFR do exist in tumor cells, one may speculate that by altering the EphA2 interactome Ephrin B3 may influence such EphA2/EGFR heterodimers and in this way control Akt Ser 129 and EphA2 Ser897, resulting in block of EphA2 mediated invasion/migration signaling." (PMID 27533087, 2016). "However, resistance to EGFR inhibitors may result from an EGFR-independent aberrant activation of the PI3K-AKT1-mTOR pathway in tumor cells." (PMID 26784176, 2016). "Therefore, we hypothesized that TAZ might also contribute to GBM cell proliferation and tumor formation through EGFR pathway." (PMID 27167112, 2016). "Peculiar Src expression and kinase activity have been found in a number of different tumours, including GCs; these changes in expression could upregulate tyrosine phosphorylation of Cav-1 and inhibit the effects of the cell membrane on EGFR endocytosis." (PMID 27105508, 2016). "However, some patients with RAS WT tumor have primary resistance to anti-EGFR mAbs." (PMID 27916952, 2016). "Therefore, neutralizing this tumor response to radiation by inhibiting EGFR signaling could maintain tumor sensitivity." (PMID 27245053, 2016).
tumor (continued). "Regarding clinical data, 5 of 22 patients included in this work died during this study, of which four(patient 4, 6, 8 and 9) had CTCs isolated with anti-EGFR (3, 2, 9 and 4 CTCs, respectively) while patient 11, who had no CTCs in the EGFR fraction, died from a tumour-independent cause." (PMID 27711186, 2016). "EGFR gene amplification was associated with deep invasion (pT3–pT4 versus pT1–pT2; Fisher’s exact test, p = 0.020; OR 3.49, 95 % CI: 1.17–10.4) and it was more commonly detected in stage III–IV tumours than in stage I–II tumours (Fisher’s exact test, p = 0.024; OR 2.55, 95 % CI: 1.18–5.51)." (PMID 27387915, 2016). "In addition, some discordance for detection of T790M between plasma and either tumor tissue or malignant fluid samples obtained after the development of resistance to EGFR-TKIs was observed and found to be largely due to false negative results with the plasma samples." (PMID 27542267, 2016). "As EGFR is highly expressed on hepatocytes in normal liver tissue, this might lead to sequestration of anti-EGFR-mAbs shortly after administration and interfere with effective tumor targeting." (PMID 27252651, 2016). "Finally, none of the 5 cases with wildtype RAS in the primary tumour subsequently developed RAS mutations in the EGFR-targeted therapy relevant “hotspot” codons." (PMID 27756406, 2016). "Therefore, we demonstrated that tumor may compensate strategies targeting IGF1R by activating alternative EGFR downstream signaling pathway." (PMID 27105537, 2016). "In addition, the EGFR-positive CTCs were assessed using CellSearch® Tumor Phenotyping Reagent EGFR." (PMID 27916908, 2016). "Similarly cross-reactive Cetuximab was used to image tumor EGFR expression in patients." (PMID 26848870, 2016). "We investigate the lipidome of lung pleural effusion (PE) for unique metabolic signatures to discriminate benign versus malignant PE and EGFR versus non-EGFR malignant subgroups to identify novel diagnostic markers that is independent of tumour cell availability." (PMID 27739449, 2016). "Magnetic beads coated with anti-EpCAM or anti-EGFR could isolate tumour cells with high efficiency." (PMID 27711186, 2016). "Moreover, tumor [11C]erlotinib uptake was shown to be higher in TKI-sensitive EGFRmut tumors as compared to tumors with a wild-type EGFR, indicating that PET and [11C]erlotinib may identify patients that are sensitive to erlotinib therapy." (PMID 26857779, 2016). "Provided that microRNAs (miRNAs) negatively regulate their gene targets at the transcriptional level, it is speculated that miRNA mimetics may reduce the expression, activity and signal transduction of EGFR so that sensitization of tumour sites to gefitinib-induced cytotoxicity can be achieved." (PMID 26891293, 2016). "However, a lack of sufficient tumor tissue has been a limitation for determining EGFR mutation status in clinical practice." (PMID 27472739, 2016). "However, the results from this study pinpoint the dynamic and rapid shift of tumor phenotype and sensitivity to therapies and highlight the small window in which EGFR blockade can be most beneficial in the setting of combinations with immune-mediated anti-cancer approaches." (PMID 27685624, 2016). "In patients pretreated with chemotherapy and erlotinib or gefitinib, dacomitinib compared to placebo did not increase OS neither in patients with EGFR-mutation-positive tumours (HR 0.98, 95% CI 0.67–1.44) nor in patients with EGFR wild-type tumours (HR 0.93, 0.71–1.21; pinteraction = 0.69)." (PMID 27433281, 2016).
tumor (continued). "In innate immune resistance, oncogenic gene alterations in NSCLC, such as EGFR mutations, ALK rearrangements, and PTEN loss followed by the activation of the PI3K–Akt pathway, induce PD-L1 expression leading to the inhibition of tumor cell destruction by immune cells." (PMID 27050074, 2016). "Importantly, the outcome of patients who received EGFR TKI as first line treatment and who were tumor EGFR mutation positive or tumor and plasma positive was similar, thus confirming that NGS analysis of liquid biopsy is a suitable method for EGFR mutation testing in NSCLC." (PMID 27448974, 2016). "Wheeler and colleagues, assessing the phosphorylation specific sites Y992 and Y1068 using reverse-phase protein array, showed that intermediate or high tumor EGFR Y1068, but not Y992, phosphorylation were associated with significantly reduced PFS in a series of frozen HNSCC samples." (PMID 27556186, 2016). "Thus, EGFR-overexpressing tumor cells, which are more inclined to have a metaplastic morphology, may also be insensitive to the instillation chemotherapy." (PMID 27870887, 2016). "In summary, our data suggest that EHD3 might undergo its tumor suppressor functions at least in part through promoting the sorting of activated EGFR to the lysosomal degradative compartment and spatio-temporal regulation of EGFR signaling via ERK and AKT." (PMID 27811356, 2016). "Finally, EGFR and NRAS mutations are rare in all these three tumor entities." (PMID 27283768, 2016). "Moreover, EGFR-targeted therapy might not only directly inhibit tumor cell growth, but also modulate the tumor microenvironment." (PMID 27683110, 2016). "Also, autocrine or paracrine ligand-to-receptor loops could potentially activate EGFR, as co-expression of EGFR and TGFa was detected in the same tumor." (PMID 26646697, 2016). "Currently, however ROS1 testing is often part of a second phase of testing in a patient whose tumour is negative for more common, routinely tested alterations such as EGFR and KRAS mutation and ALK gene rearrangement and who is a lifelong never or long-time ex-smoker." (PMID 27535289, 2016). "However, more anti‐EGFR miRNAs need to be explored, as a single mRNA can be the target of hundreds of miRNAs, and combinations of multiple tumour suppressive miRNAs targeting an individual gene might improve therapeutic efficacy by reducing resistance." (PMID 27241841, 2016). "Our xenograft data suggest that intratumoural injection of miR‐134 agomir decreased the expression of EGFR and suppressed tumour growth by inhibiting proliferation and inducing apoptosis of tumour cells, suggesting that miR‐134 could be a potential strategy for EGFR‐targeted therapy." (PMID 27241841, 2016). "As EGFR inhibitors enhance the expression of antigen presenting molecules in affected skin keratinocytes, they may concurrently facilitate neo-antigen presentation in lung cancer tumor cells contributing to anti-tumor immunity." (PMID 27467256, 2016). "Although NGS was quite sensitive to detect EGFR mutations in plasma, the agreement between tissue and plasma for additional coexisting mutations identified in EGFR mutant NSCLC was low, thus preventing the possibility to have a comprehensive picture of tumor heterogeneity using liquid biopsy." (PMID 27448974, 2016). "In addition, CTCs could be detected in 42.9% of patients with an altered EGFR status in the primary tumour." (PMID 27302574, 2016). "In immunohistochemistry analysis, neoplasms with low versican expression showed greater EGFR immunostaining in the in situ areas than in invasive areas, even as the group presenting high versican expression displayed greater EGFR and HER-2 staining in in situ areas." (PMID 27490467, 2016). "Furthermore, ectopic activation of Src, EGFR, PI3K or Yki in simple columnar imaginal discs is sufficient to induce overproliferation of cells, whereas loss of PI3K or Yki strongly impairs imaginal disc tumour formation." (PMID 26989177, 2016).